PGR (progesterone receptor)
Diseases named in the same sentence as PGR in open-access papers (continued):
Sharing a sentence is not in itself a finding about the gene and the disease.
cervical carcinoma (11 papers, 1997 to 2025). A carcinoma arising from either the exocervical squamous epithelium or the endocervical glandular epithelium. "In the present patient, CK7 positive and CK20 negative immunohistochemical studies were consistent with her previous cervical cancer and the rate of ER and PgR positivity were the same as the previous cervical cancer, establishing the origin of the lesion found in the appendix." (PMID 33961143, 2021). "We investigated whether the reported in vitro effects of oestrogen and progesterone on cellular proliferation can be replicated in locally advanced cervical cancer in vivo and whether these effects, if any, are related to oestrogen and progesterone receptor (ER and PgR) content of the tumour." (PMID 9052410, 1997). "These target genes were crossed with mRNAs that are downregulated by more than fivefold in cervical cancer from The Cancer Genome Atlas (TCGA) database, and 8 target genes were finally obtained (OGN, SCN7A, PGR, PTGER3, FGF7, ADAMTS5, LMO3 and ANK2)." (PMID 35513835, 2022). "Cervical cancers that are HPV-independent show positive immunoexpression for CEA (carcinoembryonic antigen) and p16, but lack immunopositive results for estrogen receptor (ER) or progesterone receptor (PR)." (PMID 41155343, 2025). "A recent study summarized that in 60–80% cases, the progesterone receptor in the tissue of cervical carcinoma is not detectable." (PMID 36769131, 2023). "However, considering that the remaining 4 cases were negative for both ER and PgR, and most cervical carcinomas does not express these hormone receptors, their expression may be unusual in GCC." (PMID 27708230, 2016).
colon carcinoma (11 papers, 2012 to 2025). "The PC group showed abundant colonic tumours alongside increased colonic tissue testosterone levels and androgen (AR) and oestrogen (ERα) receptors, whereas E2 and P4 levels with ERβ and progesterone receptor (PGR) decreased significantly compared with the NC group." (PMID 36263327, 2022). "Moreover, E2 and P4 monotherapies equally reduced the numbers of malignant lesions and colonic testosterone levels alongside AR and ERα protein expression, whilst upregulated ERβ and PGR and promoted cell cycle arrest and apoptosis in male mice, as well as in human male colon cancer cell lines." (PMID 36263327, 2022). "Although the existence of a breast cancer CIMP (B-CIMP) has been debated, a phenotype comparable with colon cancer and the glioma CIMP has been evidenced and suggested to be prevalent in the estrogen receptor α (ERα)– and progesterone receptor (PR)–positive luminal subtypes of breast tumors." (PMID 35351824, 2022).
Hypertension (10 papers, 2015 to 2024). The presence of chronic increased pressure in the systemic arterial system. "Thirty-nine (43.3%) patients had comorbidities, including hypertension, hyperlipidemia, diabetes, coronary heart disease, and chronic lung disease, and 69 (76.7%) patients had hormone receptor (estrogen receptor and progesterone receptor) positive." (PMID 35634442, 2022). "Additionally, significant variations were observed in the distribution of patients in different parity, hypertension, histological type, maintenance treatment, estrogen receptor (ER) intensity, and progesterone receptor (PR) intensity (all P < 0.05)." (PMID 38308352, 2024). "And, in breast cancer, GLR, progesterone receptor (PR), human epidermal growth factor receptor-2 (HER-2), Ki-67, T classification, lymph node status, clinical stage, hypertension, BMI, and platelet count were significantly related to OS." (PMID 38501103, 2024). "Significant differences were found in the proportions of hypertension, diabetes, hyperlipidemia, BMI, WHR, HOMA-IR, VFA, oestrogen receptor, progesterone receptor, HER2, E2, and LH between the two groups (P<0.05)." (PMID 40777932, 2024). "Waist circumference, hypertension, diabetes, hyperlipidemia, BMI, HOMA-IR, WHR, VFA oestrogen receptor, progesterone receptor, HER2, E2, and LH showed statistical differences (P<0.05)." (PMID 40777932, 2024).
metastatic carcinoma (10 papers, 2012 to 2023). A carcinoma which has spread from the original site of growth to another anatomic site. "Immunohistochemically, primary and metastatic cancer cells were diffusely positive for chromogranin A and the estrogen receptor (Allred's total score: 8) and focally reactive for synaptophysin and the progesterone receptor (total score: 5)." (PMID 36572422, 2022). "The diagnosis of metastatic carcinoma was made based on immunostaining data for the estrogen receptor (ER), progesterone receptor (PR) and CerbB-2 in neoplastic cells." (PMID 23833651, 2013).
diabetes (9 papers, 2014 to 2025). "In our model, we identified five differentially expressed diabetes-related genes, with GSN and PGR exhibiting heightened expression levels in the low-risk group, whereas CDKN2A, SELENOP, and TRPC1 demonstrated increased expression in the high-risk group." (PMID 41244925, 2025). "Furthermore, stratification of UCEC patients by diabetic status revealed that the dysregulation of SELENOP, CDKN2A, and PGR was specifically exacerbated by diabetes." (PMID 41244925, 2025). "To further validate the protein expression levels of the five key diabetes-related genes (CDKN2A, GSN, PGR, SELENOP, and TRPC1) identified in our prognostic model, we utilized IHC staining data from the HPA database." (PMID 41244925, 2025). "Nonetheless, the new selective antagonist C113176 may be of some therapeutic advantage for treatment of the metabolic features of hyperglucocorticoidemia/diabetes since it does not bind to the progesterone receptor." (PMID 24642683, 2014).
glioma (9 papers, 2017 to 2026). A benign or malignant brain and spinal cord tumor that arises from glial cells (astrocytes, oligodendrocytes, ependymal cells). "In IDH-wt glioma, PGR, COL17A1, and RGS14 showed strong predictive value for recurrence, consistent with their known roles in tumor aggressiveness and therapy resistance." (PMID 41139924, 2025). "In IDH-wt glioma, our approach identified PGR, COL17A1, and RGS14 as key predictive markers for recurrence, consistent with their known roles in tumor aggressiveness and therapy resistance." (PMID 41139924, 2025). "In high-plasticity glioma stem cells, the genetic expression of the progesterone receptor (PR) was higher than in healthy stem cells, implicating progesterone in glioma stem cell proliferation." (PMID 39202716, 2024). "The progesterone receptor was expressed in five glioma patients, and expression of the oestrogen receptor was found in only one woman, who had a malignant prolactinoma." (PMID 31882734, 2019). "Gliomas were found to exhibit the lowest PGR expression compared to other PR-dependent cancers." (PMID 41439468, 2026). "Both of PGR and AR have been reported to play important roles in glioma." (PMID 35120529, 2022). "This locus was previously associated with estrogen- and progesterone receptor-negative breast cancer, glioma, prostate, testicular germ cell, pancreas, and urinary bladder." (PMID 33909215, 2021). "Fibronectin, Rad51, Cyclin-E1 and Progesterone Receptor are also shown, along with supporting box plots from the IDH-wt grade II/III glioma vs GBM expression data, and demonstrated higher expression in the PN and GBM samples." (PMID 29142297, 2017).
apocrine carcinomas (8 papers, 2013 to 2026). "Apocrine carcinoma (AC) of the breast is a rare histological subtype, classically characterized by androgen receptor (AR) positivity with estrogen receptor (ER) and progesterone receptor (PR) negativity." (PMID 41873263, 2026). "According to emerging evidence, apocrine carcinomas tend to show estrogen and progesterone receptor negativity and androgen receptor positivity (ER−/PR−/AR+); and expression of Gross cystic disease protein fluid-15 (GCDPF-15)." (PMID 23864975, 2013). "Apocrine carcinomas are often estrogen receptor (ER)- and progesterone receptor (PR)-negative, with 30% of them having human epidermal growth factor 2 (HER2) amplification." (PMID 35329934, 2022). "Both apocrine carcinomas were immunohistochemically negative for estrogen receptor (ER) and progesterone receptor (PgR), but diffusely positive for androgen receptor (AR), GCDFP-15, and HER2." (PMID 25309767, 2014). "Almost all intraductal and invasive apocrine carcinomas are positive for GCDFP-15/AR and negative for ER and PgR." (PMID 36553136, 2022). "PIK3CA mutations and PTEN protein expression (IHC) were analyzed in luminal tumors (ER and/or PgR positive), molecular apocrine carcinomas (MAC; ER/PgR negative / AR positive) and hormone receptor (ER/PgR/AR) negative tumors." (PMID 26452060, 2015). "It has been reported that metaplastic carcinomas are consistently negative for ER and PgR and generally do not overexpress HER2; however, the present case maintained extensive HER2 positivity not only in the apocrine carcinoma including the intraductal components but also in the spindle cell lesion." (PMID 25309767, 2014).
endometrial adenocarcinoma (8 papers, 2009 to 2026). "Progesterone receptor is less frequently seen in mucinous endometrial adenocarcinoma compared to endometroid endometrial adenocarcinoma." (PMID 38989238, 2024). "Cytoplasmic GPER1 overexpression was also found in high-grade estrogen receptor- and progesterone receptor-negative endometrial adenocarcinomas in association with myometrial invasion and poor survival." (PMID 39252786, 2024). "The JEC cell line, derived from moderately differentiated human endometrial adenocarcinoma, exhibits unique estrogen receptor (ER)- and progesterone receptor (PR)-negative characteristics." (PMID 40708858, 2025).
inflammatory breast carcinoma (8 papers, 2010 to 2024). An advanced, invasive breast adenocarcinoma characterized by the presence of distinct changes in the overlying skin. "In addition, median OS was significantly longer in patients with non-inflammatory breast cancer (p = 0.02) and patients with ER+ disease, progesterone-receptor-positive disease, HER2+ disease, lower nuclear grade, locoregional therapy, and metastasis to a single organ (all p < 0.0001)." (PMID 34071219, 2021). "Two patients with metastatic triple-negative (estrogen receptor (ER)-negative, progesterone receptor (PgR)-negative, HER2/neu-negative) inflammatory breast cancer were included in this study." (PMID 25307991, 2014).
metastasis (8 papers, 2013 to 2024). The spread or migration of cancer cells from one part of the body (where they first appeared) to another. "Independent, significant predictors for PFS were progesterone receptor expression (HR: 0.88), multiple metastatic sites (HR: 2.56), and hepatic metastasis (HR: 2.01)." (PMID 38730711, 2024). "It is worth noting that in the three patients with lung metastasis and heart metastasis, estrogen receptor (ER) and progesterone receptor (PR) of the tumor were strongly positive, and one of the patients eventually died." (PMID 37139188, 2023). "The ILC group was correlatedwith older age, larger tumor size, later stage, lower grade, metastasis disease(M1) disease, and greater counts ofpositive lymph nodesandestrogen-receptor-positive (ER)/progesterone receptor-positive (PR) positive nodes." (PMID 28863134, 2017).
glioblastoma (7 papers, 2016 to 2026). The most malignant astrocytic tumor (WHO grade IV). "LPA stimulates PKCα–progesterone receptor (PR) interaction inducing receptor phosphorylation, and LPAR1-mediated upregulation of VEGF expression contributing toward glioblastoma progression." (PMID 34440828, 2021).
mucinous carcinoma (7 papers, 2010 to 2022). "In contrast to this, we found the mutation also in a relapsed patient with mucinous carcinoma (grade 1, ER/progesterone receptor unknown)." (PMID 27515171, 2016). "All ILC and mucinous carcinomas as well as the papillary carcinoma were ER/PgR positive." (PMID 20976182, 2010). "Most mucinous carcinomas are ER-positive and PgR-positive, regardless of patient age and histological type, and thus they are not entirely apocrine-differentiated carcinomas— they partially have apocrine character." (PMID 36553136, 2022). "Tumors of pure mucinous carcinoma are typically positive for both estrogen receptor (ER) and progesterone receptor (PR), and they do not commonly overexpress human epidermal growth factor receptor 2 (HER2)." (PMID 32871976, 2020). "The resected breast specimen revealed pure mucinous carcinoma and immunohistochemical analyses demonstrated that tumor cells were positive for estrogen receptor (ER), but negative for progesterone receptor (PgR)." (PMID 24396451, 2014).
serous carcinomas (7 papers, 2013 to 2025). "Negativity of ER and PgR staining is more reasonable with the diagnosis of serous adenocarcinoma including EIC." (PMID 23414240, 2013). "Low-grade serous carcinomas typically express WT1, CK7, PAX8, Estrogen receptor (ER), and Progesterone receptor (PR)." (PMID 33919741, 2021).
bone metastasis (6 papers, 2014 to 2024). Transfer of a neoplasm from its primary site to bones. "In addition, bone metastasis was related to a lower histologic grade, ER positivity, ER positivity and progesterone receptor (PR) negativity, strand growth patterns, and the presence of fibrotic foci in invasive ductal carcinoma." (PMID 26163388, 2015).
breast adenocarcinoma (6 papers, 2012 to 2025). "A 67-year-old woman with a history of estrogen receptor/progesterone receptor positive breast adenocarcinoma diagnosed 15 years earlier presented with hypercalcemia." (PMID 41377409, 2025). "MCF7 cells are the most frequent used in vitro models of human breast adenocarcinoma; they are estrogen-receptor positive and progesterone-receptor-positive, and they express characteristics of breast epithelial cells (Comşa, Cîmpean & Raica, 2015)." (PMID 37361049, 2023). "The resulting Nf1 indels induced highly penetrant, aggressive mammary adenocarcinomas that express estrogen receptor (ER) and progesterone receptor (PR)." (PMID 30182054, 2018). "Immunohistochemistry was used to compare relative expression levels of the hormone receptors ERα and PgR, cyclin D1, Ki67 and ErbB2 in the mammary adenocarcinomas that developed in the different genotypes across treatment groups." (PMID 24575359, 2012).
depression (6 papers, 2013 to 2026). "Suggestive evidence was observed regarding the positive association between progesterone receptor expression and risk of depression." (PMID 41992590, 2026). "Compared to the High effective action class, the Low class was more likely to have a lower annual income, more likely to report a diagnosis of depression, and less likely to have a progesterone receptor positive tumor." (PMID 35805053, 2022). "Similar to the stratified analyses by age, depression was not modified by estrogen receptor (ER)+/progesterone receptor (PR)+ status and consistently and inversely associated with each physical health measure." (PMID 34371931, 2021).
endometrial stromal sarcoma (6 papers, 2015 to 2025). "Immunohistochemical analysis showed strong positivity for CD10, estrogen receptor (ER), and progesterone receptor (PR), supporting the diagnosis of metastatic low-grade endometrial stromal sarcoma." (PMID 41018140, 2025). "Regarding uterine LMS and endometrial stromal sarcoma, the expression of estrogen receptor (ER) and progesterone receptor (PR) was frequently observed in previous studies using immunohistochemistry." (PMID 34980039, 2022). "Compared with other uterine sarcomas, positive expression rates of the estrogen receptor and the progesterone receptor are higher in endometrial stromal sarcoma, especially in low-grade endometrial stromal sarcoma." (PMID 35145981, 2021). "It has been reported that the expression of the estrogen receptor and the progesterone receptor in endometrial stromal sarcoma is positively correlated with disease-free survival and overall survival." (PMID 35145981, 2021). "Immunohistochemical staining to determine the estrogen receptor and the progesterone receptor expression may contribute to the prognosis of the patients with endometrial stromal sarcoma." (PMID 35145981, 2021).
endometrial tumors (6 papers, 2014 to 2025). "Previously established associations between estrogen receptor (ESR1) and progesterone receptor (PGR) loss of expression and poor survival are confirmed by applying receptLoss to mRNA expression data from endometrial tumors in TCGA." (PMID 32894083, 2020). "Endometrial tumors obtained at surgery (MET, n = 4; CON, n = 4) were analyzed for proliferation (Ki67), apoptosis (TUNEL), and nuclear expression of ERα, PGR, PTEN, and KLF9 proteins in tumor glandular epithelial (GE) and stromal (ST) cells." (PMID 32046384, 2020).
in situ carcinoma (6 papers, 2010 to 2021). A malignant epithelial neoplasm which is confined to the epithelial layer without evidence of further tissue invasion. "Immunohistochemical (IHC) staining indicated that the lesion was estrogen receptor(ER) negative, progesterone receptor(PR) negative, C-erbB-2 positive carcinoma in situ (3 +) and thyroid transcription factor-1(TTF-1) negative." (PMID 30453894, 2018). "Histological analysis confirmed a 20 mm IDC (grade I, oestrogen receptor (ER) and progesterone receptor (PR) positive, human epidermal growth factor receptor 2 (HER2) negative) with minimal ductal carcinoma in situ." (PMID 24708809, 2014).
medullary carcinoma (6 papers, 2005 to 2020). "In addition, negativity for progesterone receptor (PgR), a higher proportion of medullary and atypical medullary carcinomas, and tumours with a low expression of c-erbB-2 have been detected." (PMID 15642173, 2005).
migraine (6 papers, 2012 to 2023). "Polymorphisms in ESR1 and PGR may increase migraine prevalence only in some populations demonstrating an ethnic-specific effect." (PMID 24403849, 2013). "In contrast, the ESR-1 Pvu II C>T polymorphism and the progesterone receptor (PGR) PROGINS insert polymorphism do not appear to be associated with migraine." (PMID 22072275, 2012). "Reciprocal interactions between estrogen and progesterone could be integral in either prevention or maintenance of migraine because estrogen and progesterone receptors often colocalize wherein estradiol receptor activity could potentially influence progesterone receptor expression." (PMID 37795389, 2023). "This study was aimed at investigating genetic variants that are potentially related to MM, specifically undertaking genotyping and mRNA expression analysis of the ESR1, PGR, SYNE1 and TNF genes in MM cases and non-migraine controls." (PMID 25315199, 2014). "Genetic studies of hormonal genes have focused on the estrogen receptor (ESR1) and the progesterone receptor (PGR) genes, a logical choice based on fluctuating hormones of the ovarian cycle which many women recognize as triggers for their migraine." (PMID 24403849, 2013).
papillary carcinoma (6 papers, 2006 to 2025). A malignant epithelial neoplasm characterized by a papillary growth pattern. "At surgery, an infiltrative papillary carcinoma was diagnosed (receptor arrangement: ER 95%; PgR: 95%; Ki-67 7%; Her 2 negative; grading G1)." (PMID 38201413, 2024).